SNORD114-22 (small nucleolar RNA, C/D box 114-22)
Synonyms: 14q(II-22)
Gene: Small nucleolar RNA gene on chromosome 14 (100,982,926 to 100,982,997, forward strand). Ensembl gene ENSG00000202293.
Gene Ontology:
Biological process: RNA processing
Cellular component: nucleolus
Homologues: Orthologues: chimpanzee SNORD114-22 (99% identical). Paralogues in human: SNORD114-21 (93% identical), SNORD114-28 (93% identical), SNORD114-23 (92% identical), SNORD114-9 (92% identical), SNORD114-15 (90% identical), SNORD114-25 (90% identical), SNORD114-26 (89% identical), SNORD114-20 (86% identical), SNORD114-5 (85% identical), SNORD114-29 (83% identical), SNORD114-3 (83% identical), SNORD114-6 (83% identical), and 26 more.